S1PR1 (sphingosine-1-phosphate receptor 1)
Diseases named in the same sentence as S1PR1 in open-access papers (continued):
Sharing a sentence is not in itself a finding about the gene and the disease.
influenza infection (9 papers, 2013 to 2024). "Although our results confirm previous reports of the role of S1PR1 in pathology associated with infection with influenza, elucidation of the specific mechanism of S1PR1 in the inflammatory response to AIV infections requires further study." (PMID 24073762, 2013). "We examined the gene expression profile of S1PR1 to elucidate its function in influenza infection in mice challenged with H9N2 strains associated with high (V) and low (TS) pathogenicity." (PMID 24073762, 2013). "S1P/S1PR1 signaling has been implicated in viral pathogenesis in influenza infection." (PMID 30304001, 2018). "This information will not only be helpful in designing experiments to better understand the role of S1PR1 in virus-host interactions but also in developing novel anti-influenza agents to minimize the mortality and morbidity associated with highly virulent strains in avian and human populations." (PMID 24073762, 2013). "For example, previous studies report that influenza infection can alter the expression level of S1PR1 in the liver, spleen, kidney, and even heart." (PMID 34934406, 2021). "The results will contribute to get the function of S1PR1 in the infection of influenza virus and get the basic data for the strategies of anti-influenza." (PMID 24073762, 2013). "Moreover, the S1PR1 gene has been correlated with a reduction in acute lung injury induced by influenza H1N1 and plays an important role in the physiopathology of P. aeruginosa." (PMID 37233274, 2023). "The data shown in this study could provide novel insights into understanding about the regulatory role of endothelial S1PR1 in influenza infection." (PMID 30304001, 2018). "Thus, this study provided the advantages of combining antiviral drugs and S1PR1 modulators in the treatment of influenza infection." (PMID 28352271, 2017). "BALB/c mice are common laboratory animals used in research of influenza virus; however the effects of influenza infections on expression patterns of S1PR1 in mice are unknown." (PMID 24073762, 2013). "Thus, autophagic pathway affected by S1PR1 signaling in the pulmonary endothelial cells could provide a novel therapeutic target for attenuation of mortality and morbidity in influenza infection." (PMID 30304001, 2018). "Hence, we hypothesized that S1PR1 might occupy a key position in influenza inflammation, protecting the host from excessive inflammatory symptoms caused by H9N2 infection, which we demonstrated in our previous reports." (PMID 24073762, 2013). "S1PR1 inhibitor analogs, such as AAL-R and RP-002, which have already shown a protective effect from the pathophysiological response during influenza infection, have been suggested as potential immunomodulators to suppress the cytokine storm." (PMID 34934406, 2021). "In conclusion, our data showing the distribution tissue expression pattern of S1PR1 in AIV-infected mice further supports a crucial role for S1PR1 in the physiological and pathological processes in influenza." (PMID 24073762, 2013). "In comparison with BALB/c mice challenged with a highly virulent influenza strain (V), BALB/c mice challenged with the Ts showed significantly lower levels of S1PR1 mRNA in heart (P < 0.01), spleen (P < 0.01), kidney (P < 0.01), and liver (P < 0.05)." (PMID 24073762, 2013). "We found significant differences in the expression pattern of S1PR1 mRNA or protein, both between uninfected and influenza-infected BALB/c mice and between those infected with H9N2 influenza strains that are non-pathogenic and highly pathogenic in mice (TS and V strains, respectively)." (PMID 24073762, 2013).
ischemic stroke (9 papers, 2019 to 2026). A stroke disorder caused by obstruction of blood flow to the brain, due to thrombotic (local blood clot formation) or embolic (due to a blood clot or other material traveling from another site) event. "However, it has been shown that the interaction of S1P with S1PR1 can also protect the brain after ischemic stroke by inhibiting the inflammatory response and neuronal apoptosis, as well as promoting angiogenesis." (PMID 36119733, 2022). "S1P is the ligand protein for S1PR and has been identified to bind to S1PR1, S1PR2, and S1PR3 to trigger neuroinflammatory reactions in ischemic stroke." (PMID 35055089, 2022). "Activation of sphingosine-1-phosphate receptor-1 by FTY720, a known sphingosine 1-phosphate receptor agonist, is neuroprotective after ischemic stroke in rats." (PMID 31772561, 2019). "S1PR1, 2, and 3 have been shown to mediate the activation of microglial cells and the inflammatory response in male ICR mice, which may play an important role in the pathogenesis of ischemic stroke." (PMID 36119733, 2022).
Bradycardia (7 papers, 2012 to 2024). A slower than normal heart rate (in adults, slower than 60 beats per minute). "The initial activation is known to cause bradycardia through the activation of S1PR1." (PMID 39030171, 2024).
gastric cancer (7 papers, 2019 to 2024). A primary or metastatic malignant neoplasm involving the stomach. "In contrast, low S1PR1 expression was an independent risk factor for a good prognosis in gastric cancer." (PMID 32799825, 2020). "Interestingly, Gal1 has been linked with S1PR1 in gastric cancer: both proteins are overexpressed in gastric cancers, and both are associated with poor prognosis." (PMID 32388640, 2020). "Song found that there was a significant correlation between S1PR1 and chemotherapeutic drug resistance in gastric cancer, which provided evidence for the study of the mechanism and treatment of chemotherapeutic drug resistance." (PMID 33029266, 2020). "Gal1 furthermore promotes gastric cancer invasion through a mechanism dependent on S1PR1 overexpression." (PMID 32388640, 2020). "All this suggests that both Gal-1 and S1PR1 may contribute to the invasive properties of gastric cancer cells." (PMID 38570874, 2024). "A high expression level of S1PR1 was correlated with low survival rates in gastric cancer patients." (PMID 34113619, 2021). "The expression of S1PR1 in nontumor gastric tissues and gastric cancer tissues was examined." (PMID 34113619, 2021).
Insulin resistance (7 papers, 2021 to 2025). Increased resistance towards insulin, that is, diminished effectiveness of insulin in reducing blood glucose levels. "Among the eight potential key metabolites, sphinganine 1-phosphate is able to protect against the development of hepatic insulin resistance by activating the Akt pathway via the receptor subtypes S1PR1 and/or S1PR3 and by enhancing mitochondrial functions." (PMID 38201125, 2023). "In contrast, ApoM was shown to promote insulin secretion and antagonize insulin resistance after activating S1PR1 and/or S1PR3 signaling." (PMID 37867511, 2023). "The SphK1/S1PR1/STAT3 axis may enhance and amplify insulin resistance." (PMID 34751249, 2021).
liver fibrosis (7 papers, 2017 to 2025). "Systemic inhibition of S1PR1-3 isoforms reportedly attenuates development of experimental liver fibrosis in association with neovascularization inhibition in mice." (PMID 33199821, 2021). "S1P activates HSCs via S1PR2, promoting liver fibrosis, and stimulates proliferation of the hepatocytes via S1PR1." (PMID 40647361, 2025). "S1PR1/3 also play a role in ECM production in liver fibrosis." (PMID 31546702, 2019).
Autoimmunity (6 papers, 2017 to 2024). The occurrence of an immune reaction against the organism's own cells or tissues. "S1pr1, on the other hand, is involved in both cDC functions and autoimmunity." (PMID 32265909, 2020). "S1PR1 plays a role in the maturation, activation and chemotaxis of immune cells, specifically mediating migration and differentiation of macrophages, and presents a potential antigen for PAH autoimmunity, given the documented role of S1P/S1PR signaling in PAH pathogenesis." (PMID 39791702, 2024).
colorectal cancer (6 papers, 2019 to 2025). A primary or metastatic malignant neoplasm that affects the colon or rectum. "Studies have shown that S1PR1 is highly expressed in colorectal cancer and that the up-regulation of S1PR1 expression is closely related to deep infiltration of cancer cells and liver metastasis." (PMID 34484174, 2021). "Multivariate survival analysis has shown that S1PR1 expression levels can be used as an independent prognostic indicator of colorectal cancer." (PMID 34484174, 2021). "The same study found that increased expression of S1PR1 was correlated with metachronous liver metastasis and poor overall survival in colorectal cancer patients and was recognized as an independent prognostic factor." (PMID 32456134, 2020). "Up-regulation of S1PR1 and STAT3 expression was shown to correlate with poor survival of colorectal cancer patients, which additionally advocates targeting S1PR1 to attenuate malicious feed-forward amplification loop involving S1PR1/STAT3 signaling as a strategy to combat colon cancer." (PMID 32456134, 2020). "And blocking the S1PR1 signaling pathway could inhibit tumor proliferation and induce apoptosis in multiple tumor cell lines (pancreatic cancer, renal cell carcinoma, and colorectal cancer)." (PMID 31438989, 2019). "On the contrary, findings from the study based on tissue microarray and immunohistochemical analyses revealed significantly higher expression of the S1PR1 protein in the colorectal cancer lesions in comparison with adjacent non-cancerous tissues." (PMID 32456134, 2020).
diabetes (6 papers, 2011 to 2024). "It has been shown in a previous study in which the expression of S1PR1 was higher in diabetes than controls, suggesting that S1P and its receptors might play important role in diabetes." (PMID 23360427, 2013). "The expression of S1PR1 in the vitreous samples from PDR patients was upregulated by about 2.65-fold as compared to the vitreous samples from control patients without diabetes." (PMID 25496321, 2014). "We demonstrated that PLA1A, AGK, S1PR1 and SPL were detected in all vitreous fluid samples from patients with PDR and control patients without diabetes." (PMID 25496321, 2014). "Western blot analysis was used to quantify the expression levels of PLA1A, PLA2, AGK, S1PR1, SPL and 5-lipoxygenase in vitreous fluid samples from patients with PDR (n = 16) and control patients without diabetes (n = 16)." (PMID 25496321, 2014).
heart failure (6 papers, 2017 to 2025). Inability of the heart to pump blood at an adequate rate to meet tissue metabolic requirements. "This research provides a potential strategy by CM-targeted S1PR1 overexpression as a new therapeutic intervention for heart failure." (PMID 39816679, 2025). "Taken together, S1pr1 is highly expressed in cardiac ECs and up‐regulated during the process of pressure overload‐induced heart failure." (PMID 31854513, 2020). "Consistence with these investigations, our studies strongly supported that the overall notion that pharmacological activation of S1pr1 can improve cardiac remodelling and enhance cardiac functions in pressure overload‐induced heart failure." (PMID 31854513, 2020). "Previous reports and our study suggest that S1pr1 gene delivery might be a promising therapy for heart failure." (PMID 39816679, 2025). "As expected, inhibition of AKT/eNOS or blockade of sGC in vitro reversed the inhibitory effect of S1pr1‐overexpressing EC‐conditioned medium on fibroblast migration, proliferation and myofibroblasts activation, explaining the molecular mechanism by which EC‐S1pr1 prevents heart failure development." (PMID 31854513, 2020). "Furthermore, SEW2871 agonist increased capillary density and diminished cardiomyocyte size in banded hearts, suggesting S1pr1 activation improved cardiac remodelling during pressure overload‐induced heart failure." (PMID 31854513, 2020). "Taken together, our results suggest that activation of S1pr1 could ameliorate cardiac remodelling during chronic heart failure and therefore provide SEW2871 as a possible novel therapeutic target against heart failure." (PMID 31854513, 2020). "Activation of S1pr1 signalling significantly increased LVEF% and LVFS% in TAC model, indicating that SEW2871 improves cardiac function during the development of heart failure." (PMID 31854513, 2020).
ischemia (6 papers, 2015 to 2025). A hypoperfusion of the BLOOD through an organ or tissue caused by a PATHOLOGIC CONSTRICTION or obstruction of its BLOOD VESSELS, or an absence of BLOOD CIRCULATION. "Here, we evaluated the expression of S1PR1 in the hypoperfused mouse brain and investigated the effect of a selective S1PR1 agonist on leptomeningeal collateral growth and subsequent ischemic damage after focal ischemia." (PMID 26367258, 2015). "We also assessed the effect of the S1PR1 agonist on subsequent ischemic damage after focal ischemia." (PMID 26367258, 2015). "In conclusion, an S1PR1 selective agonist enhanced collateral growth and led to strong infarct size reduction after subsequent focal ischemia in a chronic hypoperfusion mice model." (PMID 26367258, 2015). "Murine studies showed that S1PR1 mediates the negative inotropic effects of S1P in the heart, whereas selective activation of S1PR3 mediated cardioprotection after ischemia/reperfusion injury." (PMID 41418457, 2025).
rheumatoid arthritis (6 papers, 2013 to 2024). A chronic, systemic autoimmune disorder characterized by inflammation in the synovial membranes and articular surfaces. "Importantly, patients with active rheumatoid arthritis had decreased circulating S1P and microvascular expression of S1PR1, suggesting a dysregulated S1P/S1PR1 axis favoring vascular permeability and vulnerability." (PMID 38855867, 2024). "In addition, FTY720 has been shown to be efficacious in the treatment of rheumatoid arthritis and similar effects are observed with the S1PR1 antagonist, TASP0277308." (PMID 23372844, 2013). "Furthermore, because crosstalk between the apoptosis molecules Fas and S1PR1 was found in the osteoclasts of rheumatoid arthritis (RA) mice, S1P was thought to be correlated with osteoclast apoptosis." (PMID 32155312, 2020).
triple-negative breast carcinoma (6 papers, 2018 to 2023). An invasive breast carcinoma which is negative for expression of estrogen receptor (ER), progesterone receptor (PR), and human epidermal growth factor receptor 2 (HER2). "The Kaplan–Meier survival analysis suggested that in non-triple-negative breast cancer, S1PR1 was correlated with poor patient survival, whereas the correlation was not significant in the triple-negative group." (PMID 30814488, 2019). "However, few studies have shown the decrease of S1PR1 in the cell line from triple-negative breast cancer." (PMID 34235182, 2021). "S1PR1 expression was not significantly different between triple-negative breast cancer and non-triple-negative breast cancer." (PMID 30814488, 2019).
Alzheimer disease (5 papers, 2016 to 2025). A progressive, neurodegenerative disease characterized by loss of function and death of nerve cells in several areas of the brain leading to loss of cognitive function such as memory and language. "It has been reported that S1PR1 activation was in a position to ameliorate hippocampal damage and spatial memory deficits of Alzheimer's disease rats." (PMID 28018679, 2016). "Furthermore, S1PR1 is involved in the neuroinflammatory response in a variety of diseases, such as Alzheimer’s disease, experimental autoimmune encephalomyelitis, cancer-induced neuroinflammation, and COVID-19 – induced neurological dysfunction." (PMID 40438602, 2025).
Arthritis (5 papers, 2016 to 2024). Inflammation of a joint. "Taken together, our findings link S1PR1 blockade leading to cleavage of membrane VE-cadherin with loss of vascular barrier integrity and severity of IC-mediated arthritis." (PMID 38855867, 2024). "Here, we assessed the contribution of vascular integrity and EC S1PR1 signaling to joint damage in mice exposed to serum-induced arthritis (SIA)." (PMID 38855867, 2024). "Mice deficient in ApoM, the chaperone on HDL that delivers S1P to S1PR1 and has particularly effective antiinflammatory effects, show amplified arthritis in response to SIA." (PMID 38855867, 2024). "Our results show that S1PR1 attenuates arthritis by increasing microvascular barrier function, and they reveal what we believe is a heretofore-undescribed mechanism for this effect of S1PR1: restraint of a metalloproteinase that cleaves VE-cadherin." (PMID 38855867, 2024). "In contrast with our findings, S1PR1 blockade using NIBR-0213 was shown to be protective in the adjuvant-induced arthritis (AIA) model." (PMID 38855867, 2024). "In a study of adjuvant‐induced arthritis, the S1PR1‐specific antagonist NIBR‐0213 can effectively prevent arthritis but may cause diffuse alveolar hemorrhage and pulmonary interstitial fibrosis." (PMID 38469546, 2024). "Recently, S001PR930 and the S1PR1 modulator IMMH1 (SYL4) inhibited the progression of arthritis in Sprague-Dawley rats, as evidenced by reduced hind paw swelling and reduced arthritis index, alongside decreased levels of pro-inflammatory cytokines and chemokines in affected joints." (PMID 37504219, 2023).
brain tumor (5 papers, 2020 to 2023). "Recent studies demonstrated that the presence of a brain tumor in mice, whether primary or metastatic, causes downregulation of S1PR1 on the surface of T cells, and leads to the homing and sequestration of T-cells in bone marrow." (PMID 32977496, 2020). "Fingolimod (FTY720), a sphingosine analog driving the internalization of S1PR1, decreased the recruitment of macrophages to the brain tumor microenvironment and induced a pro-inflammatory phenotype." (PMID 36672428, 2023). "In addition, S1PR1 was detectable in primary GBM cells (prGBM) that were isolated from a patient suffering from this brain tumor." (PMID 37686550, 2023). "S1PR1, S1PR2 and S1PR3 were shown to be elevated in patient brain-tumor samples compared to normal brain samples, and Kaplan–Meier analyses have demonstrated an association between S1PR1 and S1PR2 with patients’ survival times." (PMID 37686550, 2023). "The S1PR1, S1PR2, and S1PR3 were shown to be elevated in patient brain tumor samples compared to normal brain, while S1PR4 was not expressed, and S1PR5 remained unchanged." (PMID 32977496, 2020).
breast tumor (5 papers, 2020 to 2024). "Another study indicated that NLRP3 expression in infiltrating macrophages was significantly associated with survival and metastasis in human breast tumor via S1PR1 signaling." (PMID 34211462, 2021). "In addition, S1PR1 overexpression has been shown to promote breast tumor growth and angiogenesis." (PMID 34059068, 2021). "In naive and breast tumor‐bearing immunocompetent mice, FTY720/Fingolimod that targets S1PR1, suppressed paclitaxel‐induced neuropathic pain, astrocyte activation, the astrocyte‐secreted synaptogenic protein Sparcl1/Hevin and synapse formation." (PMID 39126272, 2024).
Cognitive impairment (5 papers, 2022 to 2024). Abnormal cognition is characterized by deficits in thinking, reasoning, or remembering. "Endothelial-specific S1pr1 knockout mice displayed protracted BBB leakage, and the chronic BBB leakiness was associated with cognitive impairment, while pharmacological inhibition of S1PR1 function led to transient BBB breach." (PMID 38916732, 2024). "Nevertheless, CNS S1PR1 activation has also been reported in conditions with cisplatin-induced cognitive impairment, and peripheral administration of either agonist or functional S1PR1 antagonist can ameliorate spatial memory impairment." (PMID 39699949, 2024).